CRP (C-reactive protein)
Diseases named in the same sentence as CRP in open-access papers (continued):
Sharing a sentence is not in itself a finding about the gene and the disease.
bacterial infection (continued). "Specificity of bacterial infection being detected at 10mg/L (i.e. the probability that non-bacterial infection does not have CRP concentration of 10 mg/L) followed with a range of effect of $10.71." (PMID 34748558, 2021). "Conversely, the absence of severe bacterial infection is indicated when s-CRP is less than 20 mg/L33." (PMID 34675320, 2021). "In conclusion, our study suggests that pre-transplantation CRP is independent of other prognostic factors for 30-day CSI post-LT, and can be integrated into tools for assessing the risk of bacterial infection post-LT or as a component of prognostic models." (PMID 34439862, 2021). "This would explain the lack of significant correlation between sCD93 and CRP or procalcitonin (the markers that most significantly increase in bacterial infections)." (PMID 34827620, 2021). "In our study, we found that CRP is non-inferior to PCT in differentiating viral from bacterial infection in LRTI patients." (PMID 34583675, 2021). "Because of the readiness and availability in most hospitals, CRP and PCT tests could be useful tools in the early differentiation of endemic febrile illness and commonly encountered bacterial infections." (PMID 32398008, 2020). "For preterm infants, the PCT level alone with a cut-off value over the 95th percentile in the serum PCT reference curve, and for term infants, the PCT level, and CRP level in combination with WBC count and/or IgM level should be used for the detection of early-onset bacterial infection." (PMID 33081061, 2020). "In addition, we also investigated the relationship between C-reactive protein (CRP) and procalcitonin, which are usually elevated in bacterial infections, as an indicator for the presence of LPS and severe clinical disease." (PMID 33207759, 2020). "C-reactive protein (CRP) is an acute phase protein and the production of CRP is stimulated by a proinflammatory cytokine, interleukin 6 (IL-6), involving in the host defense against bacterial infections." (PMID 32398008, 2020). "We did not record any laboratory values that are markers of bacterial infection like white blood cell count and C-reactive protein." (PMID 33147269, 2020). "During bacterial infections, SLE patients usually present with an adequate CRP-response which may be due to the massive increase of IL-6 that overrides the inhibitory effect of type I IFNs and/or genetic variants of CRP." (PMID 33584722, 2020). "On the basis that a test used to rule-out bacterial infection must achieve high NPV even at relatively high prior probability of bacterial infection, our data show that the combined SeptiCyteTM score outperforms WCC and CRP." (PMID 32690014, 2020). "Monitoring CRP and PCT levels help to distinguish whether there was bacterial infection in the lung." (PMID 32549071, 2020). "The detection of CRP and PCT is of certain value to distinguish whether there was bacterial infection in the lung." (PMID 32029004, 2020). "It is important to take into account that both high levels of CRP and the alterations of WBC and hepatic inflammation markers could be partly explained by concomitant bacterial infections and medications." (PMID 33297986, 2020). "Moreover, the HD patients have stronger inflammation as demonstrated with higher expression of CRP and ESR than other population owing to the HD patients that have more serious bacterial infection and are in chronic inflammatory state for a long time." (PMID 32722980, 2020). "Our data confirm the theory that CRP cannot be used as a differentiation parameter to distinguish between infectious or even bacterial and non-infectious /non-bacterial diseases in dogs." (PMID 32434519, 2020). "Based on the areas under the ROC curves, PCT (AUC = 0.896) and CRP (AUC = 0.748) performed equally well (p = 0.051) to differentiate bacterial infection from non-bacterial infection in GPP patients in the present study." (PMID 31777354, 2019).
bacterial infection (continued). "Patients with severe bacterial infection without elevation of CRP should be examined for the presence of anti-IL6 autoantibodies." (PMID 31781117, 2019). "In bacterial infections, the more specific marker is Procalcitonin (PCT), when compared to CRP." (PMID 31065202, 2019). "Neutralizing anti-IL-6 antibodies have been described in recurrent episodes of bacterial infections without an increase in C-reactive protein (CRP) level, consistent with impaired IL-6 mediated synthesis of this acute-phase reactant by the liver." (PMID 31892200, 2019). "In other (non-invasive) bacterial infections, non-bacterial infections and non-specified infections, median concentrations of CRP and PCT values were found, as expected, in the grey zone." (PMID 31664120, 2019). "These patients with fever were neither identified with clues of bacterial infection nor increased levels of C reactive protein or procalcitonin." (PMID 30792710, 2019). "CRP and PCT are two well documented indicators of bacterial infection." (PMID 31412796, 2019). "One study assessed patients in a geriatrics clinic with an elevated ESR ≥ 80 mm/h and found that a CRP > 4.36 mg/L or a leucocyte count > 8,500/mm3 was not helpful in diagnosing bacterial infections." (PMID 31315578, 2019). "CRP concentration was <10 mg/L in no single case of invasive bacterial infection, but PCT values were <0.1, <0.25 and <0.5 μg/L (see rationale for these cutoffs under Methods) in two, three and three such cases respectively (0.03, 0.09 and 0.23 μg/L)." (PMID 31664120, 2019). "We performed serologic tests, laboratory tests for procalcitonin and C-reactive protein, as well as sputum and blood cultures to rule out bacterial infection." (PMID 29794744, 2018). "Despite lacking evidence of concurrent bacterial infection, C-reactive protein (CRP) and procalcitotnin (PCT) were elevated in 94.7 and 77.7% of the patients, respectively." (PMID 29411124, 2018). "On the other hand, highest CRP was observed on day 3 of fever in patients with bacterial infection and on day 5 of fever in those without bacterial infection." (PMID 29849829, 2018). "Differentiation between viral triggered HLH and severe bacterial infection might be challenging, since inflammatory markers like CRP and PCT in nearly all patients were partly extensively elevated as commonly seen in bacterial infections." (PMID 29411124, 2018). "Several biomarker tests have been evaluated for this purpose in the context of ARIs in primary care, and C-reactive protein (CRP) has been shown to have high discriminatory power in distinguishing between viral and bacterial infections, in the range of 85–95% sensitivity and 50–75% specificity." (PMID 30323922, 2018). "The host-protein signature yielded significantly improved total accuracy as compared to prediction rules using a combination of PCT and CRP to rule-in (CRP > 80 mg/L or PCT > 2 ng/mL) or rule-out (CRP < 20 mg/L and PCT < 0.5 ng/mL) bacterial infection (p < 0.02)." (PMID 29700762, 2018). "As a nonspecific marker of inflammation, CRP plays a vital role in the monitoring of bacterial infection, inflammation, neurodegeneration, tissue injury, and recovery." (PMID 29951057, 2018). "Theconcentrations of both PCT and CRP in patients with bacterial infection werehigher than those with non-bacterial infection." (PMID 29846409, 2018). "Without evidence of bacterial infections in any of the analysed episodes, CRP was elevated in 18/19 (94.7%) with values ranging from < 0.5 to 317.5 mg/l (median 99.5, normal <8 mg/l)." (PMID 29411124, 2018). "Furthermore, systematic data on possible infectious triggers, C-reactive protein (CRP) and procalcitotnin (PCT), two parameters often used as marker for bacterial infections, are scarce or even missing in patients with HLH." (PMID 29411124, 2018). "Furthermore CRP and WCC were found to be significantly higher in patients with a co-existing bacterial infection (p = 0.004 and p = 0.0003 respectively)." (PMID 28158976, 2017).
bacterial infection (continued). "We also employed higher cutoffs (80 mg/l for CRP and 4 ug/l for PCT) to rule in patients likely require antibiotic treatment (instead of ruling out patients with a very low probability of having a bacterial infection using a lower CRP cutoff, such as 10 mg/l in the Vietnam trial)." (PMID 29059253, 2017). "Although constitutively expressed in most tissues, other CRP/SAPs did not respond to bacterial infection at the transcript level." (PMID 28336487, 2017). "In contrast to commonly used biomarkers such as C-reactive protein (CRP) and white cell count (WCC), which can be raised due to non-infective inflammatory processes, procalcitonin (PCT) has been proposed as a specific biomarker of bacterial infection." (PMID 28158976, 2017). "Despite that CRP was deemed to be nonspecific, a previous study indicated that when there is a CRP level greater than 100 mg/L, 80-85% of patients have bacterial infections." (PMID 28764651, 2017). "CRP is a well-established non-specific marker of inflammation, with sensitivity for bacterial infections usually listed around 80%." (PMID 29104224, 2017). "Host biomarkers that can help identify children with bacterial infections, such as C-reactive protein (CRP) and procalcitonin (PCT), have not been considered within the IMCI strategy." (PMID 29059253, 2017). "CRP levels increase during inflammatory states, but are not specific for bacterial infections and take more time, 6 to 48 h after start of infection, to be detectable compared to PCT." (PMID 27048405, 2016). "Assays for detecting host biomarkers associated with bacterial fevers, such as C-reactive protein (CRP) and procalcitonin (PCT) are used in hospitals in Europe to differentiate between bacterial and non-bacterial infections, and guide triage and treatment decisions." (PMID 27559728, 2016). "An accompanying immune response with elevated MxA is suggestive of a true rhinoviral or coronaviral infection while CRP elevation in the absence of elevated MxA suggests a bacterial infection." (PMID 26672961, 2015). "It is well known that PCT is positively correlated with bacterial infection and severity of infection, but also is not attenuated by steroids and has a more helpful than CRP." (PMID 26446077, 2015). "Therefore, high PCT level is more specific marker than CRP, ESR and WBC counts for the detection of bacterial infection in RA patients." (PMID 26182343, 2015). "In isolation, neither MxA nor CRP alone is sensitive or specific in identifying viral and/or bacterial infection." (PMID 26672961, 2015). "In isolation, neither MxA nor CRP alone is sensitive or specific at identifying both viral and/or bacterial infection." (PMID 26672961, 2015). "Routine blood inflammatory markers (such as ESR and CRP) are not specific for bacterial infections and rise in almostany inflammatory process, while also accounting from important variation in relation to age, sex, and race." (PMID 24696696, 2014). "The Lab-score, based on the combined determination of procalcitonin, C-reactive protein and urinary dipstick results, has been shown accurate in detecting serious bacterial infections (SBI) in children with fever without source (FWS) on retrospective cohorts." (PMID 25503770, 2014). "Serum ATX levels were apparently not influenced by bacterial infections as it did not correlate with CRP levels or white blood cell count." (PMID 25062038, 2014). "In patients admitted to the ICU with suspected H1N1 pneumonia, PCT is a sensitive marker with good negative predictive value for the identification of bacterial infection and is superior to CRP." (PMID 24612487, 2014). "None of the 13 cirrhotic patients with low CRP levels presented with clinically manifested bacterial infection." (PMID 23446058, 2013).
bacterial infection (continued). "Of 178 eligible patients, 108 (60.7%) had febrile bacterial infections (mean CRP: 63.77 mg/L, mean CRPv: 3.61 mg/L/hour) and 70 (39.3%) had non-bacterial febrile illnesses (mean CRP: 23.2 mg/L, mean CRPv: 0.41 mg/L/hour)." (PMID 19351421, 2009). "• CRPv distinguishes febrile bacterial infections from non-bacterial febrile illnesses better than CRP alone." (PMID 19351421, 2009). "• CRPv distinguishes febrile bacterial infections from non-bacterial febrile illnesses better than CRP alone especially in patients with CRP levels less than 100 mg/L at presentation." (PMID 19351421, 2009). "As expected, the patients with bacterial infection had significantly higher CRP levels than those with non-bacterial infection (geometrical mean of 63.77 mg/L vs. 15.23 mg/L, respectively, P < 0.001)." (PMID 19351421, 2009). "Our study was not designed to assess the sensitivity of the CRP-response for severe bacterial infections that does not result in a positive blood culture for one of these bacteria." (PMID 18706087, 2008). "Overall accuracy of PCT is higher than that of CRP to differentiate bacterial infections from non-bacterial infections." (PMID 19578505, 2008). "Thus, taking these important reservations into account, there is still a real possibility that there may exist a clinically relevant age related difference in CRP response in systemic infection, at least in invasive bacterial infections not causing a positive blood culture." (PMID 18706087, 2008). "CRP, however, which is used as a non-specific marker of inflammatory events and of bacterial infection, has been used to monitor response to antibiotic treatment." (PMID 16569261, 2006). "In our analysis, the median CRP concentration ranged from 6.25 to 6.3 mg/dL; although these values were slightly above the upper limit of normal (N <5 mg/dL), they were indicative of a viral rather than a bacterial infection." (PMID 41598308, 2026). "Nonetheless, our findings indicated that blood cortisol levels, either alone or in conjunction with CRP, could be a reliable predictor of early bacterial infection in DKA, as opposed to ACTH." (PMID 39946377, 2025). "Our subanalysis of bacterial coinfection highlighted two TA proteins, TSG-6 (a tumor necrosis factor-inducible protein) and CRP (an inflammatory protein with modest specificity for bacterial LRTI in blood), that may be useful respiratory biomarkers of secondary bacterial infection." (PMID 39611811, 2025). "Additionally, studies have shown that critically ill pneumonia patients often exhibit increased NEU and CRP levels, as well as decreased LYM levels, which may be indicative of bacterial infection and compromised cellular immunity." (PMID 40529154, 2025). "The mean (SD) CRP level for bacterial infection, probable bacterial infection, probable non-bacterial infection, non-bacterial infection, and indeterminate were 41·2 mg/L, 23·3 mg/L (38·1), 22·1 mg/L (43·3), 21·0 mg/L (39·1), and 31·1 mg/L (44·5), respectively." (PMID 39177882, 2025). "In addition, their prevalence would be too low to fully explain the low CRP levels in SLE, and these antibodies would not explain the fact that severe bacterial infections, in the same patients, still lead to high CRP levels." (PMID 40632603, 2025). "Parameters such as neutrophil-to-lymphocyteratio (NLR), C-reactive protein (CRP), total leukocyte count (TLC) and procalcitonin have been frequently employed in ML frameworks todistinguish bacterial infections from non-infectious causes of systemic inflammation." (PMID 41393480, 2025). "However, in patients being symptomatic for more than 24 h, CRP detection offers a good negative predictive value to rule out bacterial infection." (PMID 40632470, 2025). "Because CRP is transcriptionally induced in the liver upon cytokine stimulation, test results may be false negative for indication of a bacterial infection at early stages of disease onset (< 24 h)." (PMID 40632470, 2025).
bacterial infection (continued). "Laboratory results showed a markedly elevated C-reactive protein (CRP) level of 272 mg/L (reference range: <10 mg/L) and a total leukocyte count (TLC) of 18.7 × 109/L (reference range: 5-15 × 109/L) with 78.2% neutrophils (reference range: 30-60%), consistent with significant bacterial infection." (PMID 40115676, 2025). "Notably, CRP and procalcitonin levels were similar in patients with and without bacterial infections." (PMID 38255230, 2024). "Compared with patients with COPD-IPA alone, we believe that patients with COPD-IPA combined with bacterial infection may have higher levels of CRP and PCT, while ESR and LDH levels do not change significantly and CER levels are uncertain." (PMID 38633749, 2024). "Although we did not directly evaluate bacterial infections, the higher CRP and neutrophil counts in patients with poor prognoses might signify bacterial infections and their impact on the prognosis." (PMID 39338941, 2024). "It was somehow expected that the lowest values for CRP would be observed, given that it is primarily a marker of inflammation of various causes and increases in such severe patients as those in the ICU, regardless of the bacterial infection." (PMID 39766187, 2024). "Furthermore, it has been demonstrated in pediatric populations that low CRP levels are not sufficient to rule out invasive bacterial infections." (PMID 38539385, 2024). "Therefore, it appears that the strong and long-term anti-inflammatory effects of immunomodulatory drugs can directly impair the production of PCT and CRP to the extent that they are no longer sufficiently induced in response to a bacterial infection." (PMID 37762882, 2023). "Liu reported that a CRP cut-off value of 60 mg/l had the best combination of sensitivity (80.7%,) and specificity (96.0%,), a positive predictive value of 91.9% and a negative predictive value of 89.8% for diagnosing bacterial infection in frail elderly." (PMID 37737163, 2023). "Among diverse patient populations, however, there are individuals who exhibit low levels of inflammatory markers, even in the presence of bacterial infections, due to comorbidities and concurrent treatment, or patients who exhibit high CRP levels even in the absence of bacterial infections." (PMID 38137581, 2023). "Compared to CRP, the major advantage of PCT is its specificity in differentiating bacterial infection from inflammatory syndromes due to noninfectious causes, which could also affect biomarker values observed in our study." (PMID 37275364, 2023). "In addition, CRP was lack of specificity to diagnose bacterial versus non-bacterial infections accurately." (PMID 37700315, 2023). "While a positive test indicating a bacterial infection was almost systematically followed by antibiotic treatment, a considerable proportion of patients with negative tests and low CRP levels and WBC counts were still prescribed antibiotics on clinical presumption." (PMID 37490743, 2023). "Positive and negative values for CRP and bacterial infection using optimal cut-off." (PMID 37478118, 2023). "Finally, commonly accepted biological markers (procalcitonin (PCT) or C reactive protein (CRP)) do not perform as accurately in older adults for bacterial infection diagnosis." (PMID 38093181, 2023). "However, CRP > 100 mg/L was reported in more cases of non-infectious inflammatory diseases (38 cases) and other bacterial infections (41 cases) than in BSIs (12 cases)." (PMID 36482449, 2022). "Notably, there is no standard cutoff level to diagnose bacterial infections, a low CRP level does not exclude bacterial infection, and a high CRP level can also occur in the absence of bacterial infection." (PMID 36095013, 2022). "Therefore, we speculated that the nCD64 index is a superior indicator in monitoring bacterial infections and evaluating the efficacy of antibiotic therapy than conventional indicators, such as WBC, NLR, CRP, and PCT." (PMID 36443747, 2022).